HMGB1 (high mobility group box 1)
Diseases named in the same sentence as HMGB1 in open-access papers (continued):
Sharing a sentence is not in itself a finding about the gene and the disease.
autoimmune disease (continued). "Extracellular HMGB1 in its reduced form with a disulfide bond connecting C23 and C45 exhibits a cytokine-inducing activity and participates in the pathological processes of numerous inflammatory and autoimmune diseases." (PMID 30139371, 2018). "The role of HMGB1 in autoimmune disease was first confirmed in rheumatoid arthritis (RA)." (PMID 30410469, 2018). "One possible mechanism for HMGB1’s role in autoimmune diseases is that it may induce muscular dysfunction in PM /DM patients." (PMID 27537498, 2016). "In addition, extracellular HMGB1 also contributes to the pathogenesis of various chronic inflammatory and autoimmune diseases." (PMID 27634894, 2016). "The findings on RAGE, HMGB1 and their respective other ligands and receptors may warrant further study in autoimmune disease and cancer to elucidate therapeutic targets." (PMID 24705787, 2014). "In addition, extracellular HMGB1 is involved in the pathogenesis of autoimmune diseases, as evidenced by the presence of anti-HMGB1 autoantibodies in sera from RA and drug-induced SLE patients." (PMID 23734163, 2013). "Th17 cells and their specific transcription factor or related cytokines are being recognized as important mediators in inflammatory and autoimmune diseases including RA, but relatively little is known about HMGB1 roles and the relationship between Th17 and HMGB1 in RA." (PMID 22110531, 2012). "Extracellular HMGB1 has been identified as a proinflammatory mediator and, owing to its proinflammatory and immunostimulatory properties, has been proposed to contribute to the pathogenesis of multiple chronic inflammatory and autoimmune diseases." (PMID 22348591, 2012). "HMGB-1 protein is localized in the nucleus of most cells, may be secreted into the extracellular medium, and contributes to inflammation as well as to the pathogenesis of different inflammatory and autoimmune diseases." (PMID 36766961, 2023). "It is now widely accepted that alarmins (such as HMGB1 and certain S100 proteins) can stimulate innate immunity, trigger antigen-presenting cells, and activate adaptive immune responses, playing a key role in the pathogenesis of inflammatory and autoimmune diseases." (PMID 36569840, 2022). "Thus, HMGB1 plays a pivotal role in the pathogenesis of autoimmune diseases and may constitute a potential therapeutic target." (PMID 28649578, 2017). "HMGB1, which may act as a proinflammatory mediator, has been proposed to contribute to the pathogenesis of multiple chronic inflammatory and autoimmune diseases including systemic lupus erythematosus (SLE); however, the precise mechanism of HMGB1 in the pathogenic process of SLE remains obscure." (PMID 26078984, 2015). "Additionally, several reports provide evidence suggesting that HMGB1 may contribute to Th17 cells proliferation and activation in the context of autoimmune disease, including rheumatoid arthritis, myocarditis, as well as acute allograft rejection." (PMID 23519706, 2013). "As therapeutic targeting of HMGB1 has been found to be protective against tissue injury in various preclinical inflammatory disease models, HMGB1 blocking may be of future interest in the development of new treatment strategies in autoimmune disease and also in SLE." (PMID 22348591, 2012). "Importantly, in autoimmune diseases the high mobility group box 1 (HMGB1) protein was identified as a component of immune complex-containing DNA or RNA, which may act as endogenous IFN-β inducer." (PMID 21970718, 2011). "Evidence increasingly underscores the centrality of HMGB1 and NLRP3 in promoting chronic inflammation and multi-organ damage across a spectrum of diseases, including autoimmune disorders, trauma, and stress." (PMID 40688353, 2025). "High mobility group box 1 (HMGB1) plays an essential role in various pathological conditions, including inflammation, fibrosis, autoimmune diseases, and carcinogenesis." (PMID 39830661, 2024).
autoimmune disease (continued). "High serum levels of neurofilament protein light subunit (NFL), high mobility group box 1 (HMGB1), Matrix metalloproteinase-9 (MMP-9) and have been reported in several autoimmune diseases." (PMID 38463908, 2024). "An increase in serum levels of HMGB1 was also seen in these patients, suggesting a role of HMGB1/RAGE in the progression of the autoimmune disease." (PMID 39766257, 2024). "This miRNA targets the 3′-UTR of high mobility group box-1 (HMGB1), a protein with increased expression in many autoimmune diseases, and through miR-142-3p, PPARγ thus contributes to maintaining reduced HMGB1 expression." (PMID 34638914, 2021). "Similar to S100 proteins, HMGB1 is a DAMP and has been investigated in autoimmune diseases, including RA, systemic lupus erythematosus (SLE) and juvenile SLE." (PMID 34963488, 2021). "Consistently, miR-129-5p mimic prevented NF-kB signaling in autoimmune diseases by inhibiting TLR4 or TLR2-HMGB1 pathway and attenuated neuroinflammation after ischemia-reperfusion by inhibiting HMGB1 and the TLR3-cytokine pathway." (PMID 34360881, 2021). "In this study, we assessed the correlation of serum HMGB1 and anti-HMGB1 antibodies concentrations with disease activity indicators (CRP and ESR) in FUO infectious disease subgroups and autoimmune disease subgroups using the bivariate correlation analysis." (PMID 33658546, 2021). "That HMGB1 with the receptors CXCL12 and CXCR4 is also involved in autoimmune diseases has already been reported." (PMID 34943212, 2021). "High Mobility Group Box 1 (HMGB1) is a cytokine playing an important role in the pathogenesis of numerous inflammatory and autoimmune diseases." (PMID 32796569, 2020). "High mobility group box 1 (HMGB1) is a protein that acts as a DAMP when is located outside the cell, promoting the pathogenesis of autoimmune diseases." (PMID 27199979, 2016). "Although HMGB1 is not a conventional immune checkpoint molecule, and its inhibitors are predominantly used in the treatment of autoimmune diseases, it plays significant role in immune modulation and tumor immunotherapy." (PMID 41153357, 2025). "Interestingly, C1s can cleave high-mobility group box 1 (HMGB1) protein, a notable auto-antigen in autoimmune diseases." (PMID 36275687, 2022). "HMGB1 is a non-histone nuclear protein that acts as an alarm agent to drive the pathogenesis of inflammatory and autoimmune diseases." (PMID 35571092, 2022). "In autoimmune disease, such as SLE, DNA covariates with large amounts of neutrophil proteins including LL37 (a cathelicidin antimicrobial peptide) and high-mobility group box 1 (HMGB1), to activate plasmacytoid DCs (pDCs)." (PMID 35686129, 2022). "The results showed that serum HMGB1 concentration moderately correlated with CRP concentration in infectious subgroup, while serum anti-HMGB1 antibodies were strongly correlated with ESR in autoimmune disease subgroup." (PMID 33658546, 2021). "At present, anti-HMGB1 antibodies are generally considered to be related to autoimmune dysfunction, but the role of HMGB1/anti-HMGB1 antibodies in the occurrence and development of autoimmune diseases has not been fully elucidated." (PMID 33658546, 2021). "HMGB1, IL-33, S100A7, and S100A12 were chosen as the most promising alarmins according to the literature, because they were reported to be elevated in various autoimmune diseases, yet their role in pathophysiology of psoriasis is still unclear." (PMID 32377165, 2020). "With the absence of pathogens, endogenous molecules (e.g., HMGB1 is passively released from necrotic cells or secreted by stressed cells to respond to cellular injury) activate APCs, resulting in autoimmune diseases and transplant rejections." (PMID 33133061, 2020). "High levels of HMGB1 released into the extracellular milieu and its persistence in the microenvironment can contribute to the pathogenesis of many if not all autoimmune disorders and is a key factor that drives inflammation further and worsens symptoms." (PMID 31379812, 2019).
autoimmune disease (continued). "HMGB1, a highly conserved non-histone nuclear protein, was proven to be involved in the pathogenesis of inflammatory and autoimmune disease, and it can serve as endogenous alarmin to alert the innate immune system to promote host defense or tissue repair." (PMID 30410469, 2018). "This review aims to outline today’s knowledge of structure, intra- and extracellular functions including mechanisms of release and finally the clinical relevance of HMGB1 and RAGE as clinical biomarkers in therapy monitoring, prediction and prognosis of malignant and autoimmune disease." (PMID 26854151, 2015). "Also, HMGB-1 is a mediator of inflammation, as a ligand of TLR2, TLR4, and RAGE, that can promote ECM degradation and activate cell autophagy, and it has been involved in various autoimmune diseases (e.g. rheumatoid arthritis)." (PMID 41225346, 2025). "The best characterized and clinically relevant DAMP include high-mobility group box 1 (HMGB1), S100 proteins S100A8/A9/A12, heat shock proteins HSP60 and HSP70, β-defensins, and the cathelicidin LL-37, turning them into attractive therapeutic targets of chronic inflammatory and autoimmune diseases." (PMID 36275673, 2022). "Correlation analysis showed that serum concentration of HMGB1 was moderately correlated with CRP in infectious diseases subgroup, and the serum concentration of anti-HMGB1 antibodies was strongly correlated with erythrocyte sedimentation rate in autoimmune disease subgroup." (PMID 33658546, 2021). "Third, although we have excluded conditions that may confound HMGB1 secretion such as malignancy and infection, HMGB1 may be secreted by various disease conditions such as autoimmune diseases that may not have been fully controlled in our study." (PMID 32286371, 2020). "High mobility group box‐1 (HMGB1), initially described as a nonhistone nuclear protein with transcriptional regulatory properties, is now recognized as a proinflammatory cytokine in the pathogenesis of various inflammatory and autoimmune diseases, including psoriasis." (PMID 38414294, 2024). "It is also important to acknowledge that elevation in serum HMGB1 is not specific to cutaneous hypersensitivity reactions, and has been observed in HIV, epilepsy and a number of other inflammatory and autoimmune diseases." (PMID 30613954, 2019).
atherosclerosis (112 papers, 2008 to 2025). A disease characterized by the build-up of fatty material and calcium deposition in the arterial wall resulting in partial or complete occlusion of the arterial lumen. "In a recent study by Zhang and collaborators, the authors also proved that HMGB1 takes part in vascular calcification, another feature that is typically associated with atherosclerosis." (PMID 39194749, 2024). "Another phenomenon that is regulated by HMGB1 and implicated in the pathogenesis of atherosclerosis is that of endoplasmic reticulum (ER) stress." (PMID 39194749, 2024). "Studies have demonstrated that HMGB1 affects the behaviour of various cells associated with atherosclerosis, including VSMCs, endothelial cells, macrophages, and T cells." (PMID 39194749, 2024). "Vulnerable plaques are the major cause of ischemic lesions in vital organs due to atherosclerosis, and HMGB1 also plays a vital role in plaque vulnerability." (PMID 37062906, 2023). "The role of HMGB1 in the development of atherosclerosis has been demonstrated in mice deficient in apolipoprotein E, which were fed high-fat products." (PMID 33114431, 2020). "Recent reports have implicated the role of HMGB1 in endothelial dysfunction, ischemic injury, myocardial infarction, and atherosclerosis." (PMID 31336567, 2019). "It has been shown that neutralization of HMGB1 reduces development of atherosclerosis in apolipoprotein E-deficient mice, suggesting significant contribution of decreased HMGB1 by Ipra to the inhibition of vascular remodeling." (PMID 31234839, 2019). "The role of HMGB1 in the formation of atherosclerosis has been reported in apolipoprotein E deficient mice fed with a high-fat diet." (PMID 29054968, 2017). "HMGB1-treated vascular endothelial cells were used to investigate the mechanisms underlying atherosclerosis." (PMID 25884983, 2015). "HMGB1 was found to play a remarkable role in atherosclerosis-associated inflammation by signaling via receptor for advanced glycation end products (RAGE) and Toll-like receptors." (PMID 26221589, 2015). "Higher serum HMGB1 levels are a potential marker of subclinical atherosclerosis and CV events while lower serum sRAGE levels are associated with risk factors for CV disease and CV events." (PMID 24776932, 2014). "In this regard, recent experimental data suggest that monoclonal anti-HMGB1 neutralizing antibodies reduce the development of atherosclerosis in apolipoprotein e-deficient mice." (PMID 23284878, 2012). "HMGB1 is strongly associated with atherosclerosis and thrombosis, which may be involved in the development and progression of ischemic stroke." (PMID 38740617, 2025). "Interestingly, the expression of HMGB1 was enhanced due to chronic intermittent hypoxia, a process that is associated with sleep apnoea and the development of atherosclerosis." (PMID 39194749, 2024). "Atherosclerosis is associated with a greater presence of HMGB1." (PMID 39194749, 2024). "HMGB-1 neutralization also reduces diet-induced atherosclerosis in apolipoprotein E-deficient mice." (PMID 28789654, 2017). "HMGB1 has been implicated in the progression of atherosclerosis." (PMID 25884983, 2015). "Thus, a significant number of studies have investigated the role of HMGB1 in mediating the activities of VSMCs that could be associated with the development of atherosclerosis." (PMID 39194749, 2024). "Finally, diet-induced atherosclerosis in ApoE-deficient mice could be prevented by HMGB1 expression using ethyl pyruvate." (PMID 27713681, 2016). "The third cluster (blue, 124 items) centers on inflammation-related pathways and specific pathological conditions, incorporating both molecular mediators (Nrf2, NLRP3, HMGB1) and disease states (atherosclerosis, ulcerative colitis, liver diseases)." (PMID 40242756, 2025). "HMGB1 promotes monocyte-macrophage activation, amplifies inflammatory processes, and is a critical molecule in atherosclerosis." (PMID 38740617, 2025).
atherosclerosis (continued). "High-mobility group box 1 (HMGB1) protein is among the most thoroughly studied DAMPs in the context of atherosclerosis, with macrophages identified as a particularly noteworthy source of HMGB1." (PMID 41303445, 2025). "In atherosclerosis, HMGB1 promotes smooth muscle cell proliferation, migration to the intimal layer, and release of increased amounts of HMGB1 and C-reactive protein, as well as the expression of MMP2, MMP3, and MMP9." (PMID 38740617, 2025). "The aim of this article is to summarise current evidence that HMGB1, S100 proteins, and IL-33 play roles in the pathogenesis of atherosclerosis and myocardial infarction." (PMID 39194749, 2024). "Pathophysiological insights reveal that HMGB1 plays a significant role in the onset and progression of a vast array of diseases, viz., atherosclerosis, kidney damage, cancer, and neurodegeneration." (PMID 39682695, 2024). "This reduction in HMGB1-inhibiting protein levels play a crucial role in driving the onset of atherosclerosis." (PMID 39682695, 2024). "In rats with diabetes mellitus and atherosclerosis, treatment with the HMGB1 inhibitor gycyrrhizic acid was able to reduce the levels of pro-inflammatory mediators in the serum and aortas of animals." (PMID 39194749, 2024). "Elevated concentrations of HMGB-1 and IL-6 have also been correlated with the occurrence of CVDs, including myocardial infarction and atherosclerosis." (PMID 39876967, 2024). "In summary, HMGB1 plays a crucial role not only in the onset of atherosclerosis but also drives its progression episodes." (PMID 39682695, 2024). "Overall, HMGB1 plays a significant role in the formation of atherosclerosis, potentially mediating inflammation and cell necrosis through the TLR4 signaling pathway." (PMID 38493291, 2024). "When CMEC injury occurs in advanced atherosclerosis, miRNA-218 expression is likewise decreased to increase high mobility group protein B1 (HMGB1) expression." (PMID 38545341, 2024). "During atherosclerosis, HMGB1 is released by activated macrophages, leading to their apoptosis and promoting the expression of other inflammatory factors." (PMID 38493291, 2024). "Few recent studies indicated the signaling pathway of TUG1 by increasing TNF via the activation of the NF-KB pathway by regulating miR-26a/HMGB1 and development of atherosclerosis through modulating miR-21/phosphatase." (PMID 37736902, 2023). "Elevated levels of HMGB-1 have been demonstrated in animal models of atherosclerosis, hypertension, CAD, MI, and HF." (PMID 37299525, 2023). "In atherosclerosis, activation of HMGB1 and RhoA/Rac1 is closely related to vascular inflammation induced by NF-κB phosphorylation in endothelial cells." (PMID 35674581, 2022). "During the formation of atherosclerosis, HMGB1 is abundantly expressed in ECs, vascular smooth muscle cells, and macrophages." (PMID 36544080, 2022). "In the development of atherosclerosis, HMGB1 mediates the expression of proinflammatory mediators of endothelial cells during the initial stage of plaque formation, including TNF-α, IL-8, MCP-1, adhesion molecules (ICAM-1, VCAM-1), MIP-1α, and MIP-1β." (PMID 36176426, 2022). "It is likely that common triggers of innate memory such as infections in conjunction with the disease-specific stimuli including oxLDL, LDL and high-mobility group box 1 (HMGB1), can induce trained immunity in atherosclerosis." (PMID 35872901, 2022). "TLRs bind to RAGEs to amplify the inflammatory response, an important mechanism that promotes atherosclerosis, and HMGB1 is the only known receptor with the highest affinity." (PMID 36704514, 2022). "In atherosclerotic lesions in human carotid, BCN1 was found to co-localize with HMGB1 and were both found in foamy macrophages suggesting an interplay between HMGB1 and autophagy in atherosclerosis." (PMID 33912566, 2021).